MYCN (MYCN proto-oncogene, bHLH transcription factor)
Diseases named in the same sentence as MYCN in open-access papers (continued):
Sharing a sentence is not in itself a finding about the gene and the disease.
brain tumors (continued). "Both milciclib and zotiraciclib penetrates the BBB making them highly interesting to study further in MYCN-driven brain tumors, perhaps even in combination." (PMID 33585252, 2020). "In this review, we will discuss efforts made to circumvent the difficulty of targeting MYCN specifically by using direct or indirect measures to treat MYCN-driven brain tumors." (PMID 33585252, 2020). "We previously used two different MB models to show that brain tumors became addicted to the MYCN oncogene and that MYCN stabilization was required for MB development." (PMID 29511348, 2018). "Elevated c-MYC/MYCN initiates and drives tumorigenesis in many in vivo model systems of pediatric brain tumors." (PMID 28333115, 2017). "For neuroblastoma (NB), pediatric brain tumor condition, the ratio of antisense MYCN to MYCN is directly correlated with NB disease stage." (PMID 21311100, 2010). "Despite efforts have been made to reduce MYCN levels to improve prognosis across multiple cancer types, including pediatric brain tumors, further research is essential to refine therapeutic strategies and enhance survival outcomes in patients with MYCN-amplified tumors." (PMID 40365336, 2025). "This trial excluded patients with CNS tumors, leaving the efficacy of BMS-986378 on MYCN-overexpressing pediatric brain tumors unknown." (PMID 40365336, 2025). "MYCN expression, role and clinical relevance in other pediatric non-brain tumors." (PMID 40365336, 2025). "In the present study, we investigated, whether an additional MYCN amplification was able to rescue this phenotype or would even give rise to brain tumors." (PMID 33387268, 2021). "Most importantly, Brg1 deficiency in combination with overexpression of MYCN in hGFAP positive NSCs does not result in brain tumor formation." (PMID 33387268, 2021). "Interestingly, MYCN amplification was detected in one grade II spinal tumor that was classified as a “Plexus tumor” by the Heidelberg brain tumor classifier." (PMID 34041479, 2021). "These separate findings need to be further investigated to understand how these inhibitors could be used against MYCN-driven brain tumors." (PMID 33585252, 2020). "We will further consider the mechanism of action of these measures and suggest which molecularly defined brain tumor patients that might benefit from MYCN-directed precision therapies." (PMID 33585252, 2020). "In MYCN-driven human brain tumor models generated from primary embryonic or induced pluripotent stem cell (iPSC)-derived neural stem cells we could show a significant correlation of mTOR pathway activation and OCT4 levels." (PMID 33585252, 2020). "Similarly, MYCN-driven GTML brain tumors display a rapid onset of senescence and regression of tumor proliferation upon MYCN depletion." (PMID 28333115, 2017). "Indeed, in a model where human MYCN drives MB formation from the glutamate transporter 1 (Glt1) promoter in cerebellar cells, the majority of the developed brain tumors are actually Shh-independent." (PMID 22348395, 2012). "In contrast, CREBBP loss or MYCN overexpression alone in hGFAP-positive cells does not induce malignant brain tumors, as previously reported, indicating that tumorigenesis in hGFAP-cre::CrebbpFl/Fl::lsl-MYCN mice depends on concurrent alterations in both genes." (PMID 37407554, 2023). "Hence, we conclude that MYCN amplification and Brg1 deficiency disturb cerebellar development but are not sufficient to drive brain tumors originating from hGFAP or Math1 positive precursor cells." (PMID 33387268, 2021). "Since Palbociclib treatment only suppressed MYCN in combination with JQ1, we decided from now on to focus on Milciclib alone or in combination with JQ1 for targeting MYC and MYCN-driven brain tumors." (PMID 29511348, 2018). "Aberrant expression of MYCN contributes to the tumorigenesis of various embryonal and non-embryonal pediatric brain tumors by regulating important genes involved in neuronal proliferation and differentiation." (PMID 40365336, 2025).
brain tumors (continued). "On the other hand, forced expression of wild-type MYCN in the hindbrain or entire CNS does not necessarily lead to brain tumor development." (PMID 38001143, 2023). "Of note, previously generated transgenic mice, which carry a loss of Crebbp (hGFAP-cre::CrebbpFl/Fl) or an overexpression of MYCN (hGFAP-cre::lsl-MYCN) do not develop brain tumors." (PMID 37407554, 2023). "These tumors were recapitulated in hGFAP-cre::CrebbpFl/Fl::lsl-MYCN mice with a comparable frequency and latency if mice were not sacrificed due to brain tumor symptoms before non-CNS tumor development." (PMID 37407554, 2023). "Previous mouse models, which carry a knockout of Crebbp or an overexpression of MYCN in specific neural cell populations, do not develop brain tumors." (PMID 37407554, 2023). "However, with regard to certain biomarkers relevant for pediatric brain tumors (e.g., MYCC and MYCN amplification, β-catenin testing), the prognostic value has not yet been sufficiently clarified because of the rarity of these tumors." (PMID 23618424, 2013). "Also, mice with a single copy of MYCN as well as a combination of a Brg1 knockout and an overexpression of MYCN in multipotent neural stem cells or cerebellar granule neuron precursors were not adequate to drive brain tumor formation such as MB in mice." (PMID 37608807, 2023).
lung carcinoma (35 papers, 2009 to 2025). "Aberrant MYCN expression is implicated in neuroblastoma, medulloblastoma, rhabdomyosarcoma, Wilms’s tumour, prostate cancer and lung cancer." (PMID 40987316, 2025). "Laura Soucek and his colleagues suggested that MYC, MYCL and MYCN might be therapeutic targets for lung cancer and that elevated Myc levels were also associated with treatment resistance, there may be significant opportunities for the combination of Myc inhibitors with immunotherapies." (PMID 36299592, 2022). "NOB can overcome Adriamycin resistance in lung cancer cells, and enhance the chemotherapy to Adriamycin through the Akt/GSK3β/β-catenin/MYCN/MRP1 pathway." (PMID 41425709, 2025). "Specifically, MYCN overexpression promotes cell cycle progression, inhibits cytotoxic T cell infiltration, and accelerates lung cancer progression." (PMID 37415742, 2023). "KRT6A regulates the expression of G6PD through c-MYC/MYCN to promote the proliferation and invasion of lung cancer cells." (PMID 34235156, 2021). "The inhibitory relationship between MYCN and miR-34a has been evaluated in lung cancer, where miR-34a increased chemosensitivity to cisplatin via inhibition of MYCN." (PMID 34295245, 2021). "Lung cancer is unique in that all three MYC family members, c-MYC, MYCN and MYCL, are implicated in this disease and have been shown to activate or repress different subset of genes in SCLC cells." (PMID 28358317, 2017). "Some aberrations in chromosome 2 have been detected in lung cancer, for example the amplification of the MYCN locus (2p24) in SCLC." (PMID 19337251, 2009). "It has been reported that c-MYC and MYCN are amplified and/or overexpressed in lung cancer." (PMID 34235156, 2021). "c-MYC and MYCN may be used as therapeutic targets for treating lung cancer patients." (PMID 34235156, 2021). "Examples include MYCN upregulation (seen in H3.3-G34R in GBM and potentially impacted by H3.1 imbalance), silencing of tumour suppressors like p16 by H3.3-K27M and activation of oncogenic pathways such as GPR87 by H3.3 in lung cancer." (PMID 40987316, 2025). "The balance between the need for high MYCN levels during lung development and its aberrant high expression in lung cancer is not well characterized." (PMID 28358317, 2017). "However, MYCN has not attracted much attention in the treatment of lung cancer." (PMID 30486290, 2018).
childhood cancer (25 papers, 2011 to 2026). "Genomic gain of the N-Myc proto-oncogene protein (MYCN) is associated with poor prognosis in several childhood cancers." (PMID 30648000, 2019). "Genomic gain of the proto-oncogene transcription factor gene MYCN is associated with poor prognosis in several childhood cancers." (PMID 25749049, 2015). "In childhood cancer, aberrant expression of MYC and MYCN genes delineates a group of aggressive tumours responsible for a major proportion of pediatric cancer deaths." (PMID 27438153, 2016).
ovarian carcinoma (25 papers, 2008 to 2025). A malignant neoplasm originating from the surface ovarian epithelium. "Returning to clinical datasets, we investigated the relationship between MYCN and antitumor immunity in the curated ovarian cancer database, which combines data from TCGA and other independent cohorts." (PMID 38748789, 2024). "The PPI network further demonstrated that CCND1 and MYCN were at core positions in the development of ovarian cancer." (PMID 32660514, 2020). "We show that the C5 subtype of HG-SOC is defined by Let7 and MYCN de-regulation, presenting a new opportunity for targeted therapeutic intervention in ovarian cancer." (PMID 21533284, 2011). "MYCN amplification has also been frequently found in ovarian cancers." (PMID 36765581, 2023). "MYCL and MYCN gene transcripts also are overexpressed in some ovarian cancers." (PMID 36765581, 2023). "Researchers have demonstrated that oncogenes PIK3CA, MCL1, MYCN, DHFR, and eIF-5A2 were over-amplified via eccDNA in primary ovarian cancers, ovarian cancer cell line UACC-1598 and cervical cancer cell line HeLa, respectively." (PMID 37233789, 2024). "c-MYC and its paralogues MYCN and MYCL are among the most frequently amplified and/or overexpressed oncoproteins in ovarian cancer." (PMID 36765581, 2023). "We confirmed that HA@MOF@GSK-J1 intensely decreased JMJD3, MYCN, and HER2 levels; these genes are involved in epigenetic regulation, metastasis, and ovarian cancer tumor stemness." (PMID 36419626, 2022).
acute myeloid leukemia (23 papers, 2013 to 2025). Acute myeloid leukemia (AML) is a group of neoplasms arising from precursor cells committed to the myeloid cell-line differentiation. "The authors demonstrated that overexpression of MYCN rapidly caused acute myeloid leukemia in Mice." (PMID 23554972, 2013). "DNMT1 has been proved to be a key regulator in MYCN expression in patients with acute myeloid leukemia." (PMID 41142119, 2025). "Other studies have reported the overexpression of MYB, DNMT3B, and MYCN in acute myeloid leukaemia patients." (PMID 40911615, 2025). "The upregulated expression of ERG and MYCN, which are important transcription factors that are reported to be positively related to poor clinical outcomes in patients with acute myeloid leukaemia and acute lymphocytic leukaemia, seemed to induce the LSC accumulation mediated by SETD2 deficiency." (PMID 31054182, 2019). "Transplantation of bone marrow cells with ectopic expression of MYCN has been shown to induce the development of acute myeloid leukemia in mice, further supporting the oncogenic role of MYCN and suggesting that MYCN may also play a role in cancers involving myeloid cells." (PMID 39802403, 2025). "High MYCN expression was detected in five of six acute myeloid leukemia (AML) cases, in one of nine acute lymphoblastic leukemia (ALL) cases and in several leukemia cell lines." (PMID 24334727, 2014). "Amplification of MYCN is frequently found in hematologic malignancies such as lymphoma and acute myeloid leukemia (AML), considered as a well-established poor prognostic marker in these diseases." (PMID 23554972, 2013). "Amplification of MYCN (N-Myc) oncogene has been reported as a frequent event and a poor prognostic marker in human acute myeloid leukemia (AML)." (PMID 23554972, 2013). "Together, these data highlight both transcriptional and post-transcriptional regulation of MYC/MYCN by BETi in EPN, as previously reported in acute myeloid leukemia." (PMID 33668642, 2021). "GCN5 was isolated to be essential for acute myeloid leukemia (AML) cell proliferation; ADA2B and several other SAGA components were identified as selective dependencies essential for the growth and survival of MYCN-amplified neuroblastoma cell lines." (PMID 34112237, 2021).
hepatocellular carcinoma (20 papers, 2015 to 2025). A malignant tumor that arises from hepatocytes. "Lipid desaturation-associated endoplasmic reticulum (ER) stress inhibits MYCN expression via upregulating the transcriptional repressor ATF3 in hepatocellular carcinoma cells." (PMID 33614505, 2020). "MYCN, an oncogene implicated in hepatocellular carcinoma (HCC), is predominantly expressed in cancer stem-like HCC cells." (PMID 40027135, 2025). "In hepatocellular carcinoma, silencing BRD4 or MED1 repressed the transcription of SE-associated genes like SPHK1, E2F2, CCND1, MYCN, and MYC." (PMID 38443991, 2024). "Cutting-edge research has pointed out that the association of SEs with multiple oncogenes is acquired during hepatocarcinogenesis, and the increase in SEs at MYC and MYCN was observed in hepatocellular carcinoma (HCC) cells." (PMID 35757006, 2022). "Acyclic retinoid dampens MYCN gene expression and suppresses cell proliferation of MYCN-overexpressed hepatocellular carcinoma cells, at least in part by ER stress-induced ATF3 signaling pathway." (PMID 33614505, 2020). "Similarly, in hepatocellular carcinoma (HCC), p300 has been implicated in the significant reprogramming of super‐enhancers, leading to the upregulation of critical oncogenes, including MYC, MYCN, and CCND1, and fostering cancer cell proliferation both in vitro and in vivo." (PMID 38374872, 2024).
colorectal cancer (19 papers, 2013 to 2026). A primary or metastatic malignant neoplasm that affects the colon or rectum. "Nitidine chloride; Polo-like kinase 1; MYCN; Molecular dynamics simulation; Multi-omics; Spatial transcriptomics; Colorectal cancer." (PMID 42205755, 2026). "However, MYCN amplification with overexpression was observed in colorectal cancer samples more frequently with stage III and IV than with stage I and II (P = 0.0672)." (PMID 28377632, 2017).
Feingold syndrome (19 papers, 2010 to 2026). Feingold syndrome (FS), also known as oculo-digito-esophageal-duodenal (ODED) syndrome, is a rare inherited malformation syndrome characterized by microcephaly, short stature and numerous digital anomalies and is comprised of two subtypes: FS type 1 (FS1) and FS type 2 (FS2). "Less than 10% of syndromic EA/TEF are caused by de novo chromosomal aberrations, and a few monogenic syndromes are known as well (e.g., Feingold syndrome caused by MYCN pathogenic variants)." (PMID 40428346, 2025). "While MYCN variants have traditionally been associated with Feingold syndrome type 1, recent discoveries highlight gain-of-function variants, specifically p.(Thr58Met) and p.(Pro60Leu), as the cause for megalencephaly-polydactyly syndrome." (PMID 38884091, 2024). "MYCN has been indicated to be the major disease-causing gene for Feingold syndrome, a developmental disorder characterized in part by congenital heart abnormalities." (PMID 37372424, 2023). "Feingold syndrome is a skeletal dysplasia caused by loss-of-function mutations of either MYCN (type 1) or MIR17HG (type 2), which encodes miR-17-92 microRNAs." (PMID 36318514, 2022). "Feingold syndrome type 1, caused by loss-of-function of MYCN, is characterized by varied phenotypes including esophageal and duodenal atresia." (PMID 36318514, 2022). "The Feingold syndrome has been mapped to 2p23–242 and is the consequence of MYCN gene loss-of-function either by germline deletions or by coding-sequence mutations." (PMID 34926353, 2021). "The example we describe here shows some analogy to the case of Balumeiser, who, with his team, reported monozygotic female twins with Feingold syndrome associated with a mutation in the MYCN gene." (PMID 34926353, 2021). "Loss-of-function variants resulting in haploinsufficiency of MYCN, which encodes a protein with a basic helix–loop–helix domain causes Feingold syndrome (OMIM 164280, ORPHA 391641)." (PMID 34926353, 2021). "Heterozygous mutations in MYCN or MIR17HG in humans cause Feingold syndrome that is characterized by skeletal developmental defects including microcephaly, short stature, and brachysyndactyly with diminished middle phalanxes." (PMID 29636449, 2018). "Feingold syndrome is a skeletal dysplasia caused by loss-of-function mutations of either MYCN (type 1) or MIR17HG that encodes miR-17-92 microRNAs (type 2)." (PMID 29636449, 2018). "Specifically, the authors showed that syndactyly of toes 4 and 5 were more common in patients with MYCN mutations confirming the potent role of MYCN dysregulation in development is a crucial causative factor for Feingold syndrome." (PMID 28358317, 2017). "Consistently, mutations in MYCN accounted for 50% of cases in Cognet’s study into Feingold syndrome." (PMID 28358317, 2017). "Defects in MYCN cause Feingold syndrome type 1, which affects brain function including microcephaly, intellectual disability, digital malformations, and deafness." (PMID 26909693, 2016). "Furthermore, studies has shown that deletion or mutation of MYCN can cause Feingold syndrome, a condition defined by reduced brain size and learning disabilities, emphasizing the importance of MYCN expression in maintaining NPCs." (PMID 40365336, 2025). "In addition to causing tumors, MYCN is also expressed in human fetal brain, and heterozygous MYCN mutation causes Feingold syndrome characterized as reduced brain size and learning disability." (PMID 34625907, 2022). "CMA can detect copy number variants, but it cannot detect single gene disorders such as Feingold syndrome, which is an autosomal dominant condition due to mutations in the MYCN gene characterized by EAs, DAs, microcephaly, intellectual disability, and digital anomalies." (PMID 28314387, 2017). "Interestingly, loss of function, deletions or heterozygous MYCN mutations can also cause Feingold syndrome." (PMID 28358317, 2017).
Feingold syndrome (continued). "Notably, consistent with these expression patterns, heterozygous loss-of-function (LoF) MYCN variants have harmful effects on fetal development, giving rise to a genetic syndrome marked by multiple congenital anomalies known as Feingold syndrome type 1 (FS1, OMIM #164280)." (PMID 38884091, 2024). "However, whether the digestive system deficiency in Feingold syndrome 1 is the direct result of MYCN loss-of-function or a sequence effect of other developmental defects caused by MYCN mutation remains unknown." (PMID 36318514, 2022). "A similar role for N-myc in human NSC is inferred from studies demonstrating that the human microcephaly syndrome, Feingold Syndrome, is caused by mutations in MYCN." (PMID 22745758, 2012). "Pathogenic variants in the MYCN gene are the main cause of Feingold syndrome; some cases without MYCN mutations have been linked to microdeletions in the 13q31-q32 region, particularly affecting MIR17HG, which encodes the miR-17–92 cluster." (PMID 39457367, 2024). "Whole-genome comparative genome hybridization (CGH) analysis revealed microdeletions ranging from 165 kb to 17 Mb in the 13q31-q32 region in patients with skeletal abnormalities resembling Feingold syndrome, who did not have MYCN mutations." (PMID 39457367, 2024). "Other common genetic etiologies associated with EA/TEF include chromosomal disorders (trisomy 21, trisomy 18, trisomy 13), Feingold syndrome (MYCN), Fanconi anemia (multiple genes including FANCB, FANCC, FANCG, BRIP1) and other recurrent deletion and duplication syndromes." (PMID 36909054, 2023). "Feingold syndrome is a skeletal dysplasia caused by mutations in MYCN or MIR17HG, but it is not clear if these mutations lead to pathology via a common molecular mechanism." (PMID 29636449, 2018).